PLK1 (polo like kinase 1)
Diseases named in the same sentence as PLK1 in open-access papers (continued):
Sharing a sentence is not in itself a finding about the gene and the disease.
tumor (continued). "In the current research, we identified a potent inhibitory function of miR-545 on OC cell and tumor growth through the suppression of PLK1 by direct binding or an indirect regulation by abrogating KDM4B-mediated PLK1 activation." (PMID 33588776, 2021). "The synergistic antitumor effects included tumor growth suppression, silencing of the PLK1 gene, promoting tumor apoptosis, as well as the effect on cell cycle regulation." (PMID 34299020, 2021). "PLK1 was identified by an array-based screening of a customized library of tumor-lethal small interfering RNAs (siRNAs), identified in previous genome-wide screens in HNSCC tumor cell lines." (PMID 34071997, 2021). "While chemotherapy treatment increased CD133(+) cell proliferation, treatment with PLK1 inhibitors eliminated all proliferating tumor-initiating cells." (PMID 34065438, 2021). "In vivo MRI studies demonstrated significant accumulation of siPLK1-carrying SPIONs in the tumor site and efficient PLK1 silencing that significantly inhibited tumor growth." (PMID 33391494, 2021). "The overexpression of PSMB6, HSPA9, DUT, CDK7, and PLK1 was seen in resected tumor tissues compared with adjacent normal tissues, while FOLR2 was expressed more in normal tissues." (PMID 34721732, 2021). "We show that pharmacological and genetic inhibition of PLK1 remarkably enhances the anti‐tumor effect of oxaliplatin in vitro and in vivo." (PMID 34881526, 2021). "Another tumorigenic molecular mechanism of PLK1 is promoting the inactivation of tumor suppressors like the phosphatase and tensin homologue PTEN." (PMID 34065956, 2021). "Previous research from our lab also convincingly showed upregulation of Plk1 in ChREBP +/+ mice tumor and a marked reduction in its mRNA level in mouse HCC cell line by concomitant ChREBP silencing." (PMID 34685767, 2021). "Our study deciphered the phenomenon linking a physical driver of tumor aggressiveness (hypoxia) to a biological determinant of tumor cell proliferation and angiogenesis (Plk1)." (PMID 33547392, 2021). "Even though, contrarily to what was described in other tumours, lower expression of PLK-1 seems to point towards a decreased life expectancy in UM patients." (PMID 35008260, 2021). "Previous preclinical studies in GBM demonstrated an anti-tumor role of PLK1 inhibition either with TMZ or with radiation only." (PMID 34680264, 2021). "Since PLK1 can drive cell cycle progression, blocking PLK1 has been extensively explored as an antitumor strategy for various tumor types, including NSCLC 30-33." (PMID 34522178, 2021). "The core-shell structured nanoparticles-mediated 47.4% transfection of the plasmid in A375 cells in vitro and contributed to the notable downregulation of Polo-like kinase 1 protein and the corresponding tumor suppression over 67% in vivo." (PMID 34683943, 2021). "It was discovered that blocking the expression of PLK1 via siRNA can effectively inhibit the proliferation and induce the apoptosis of tumor cells." (PMID 34925510, 2021). "Since the stability of Myc was regulated directly or indirectly by PLK1 for tumor survival, the protein level of c-Myc was observed by immunoblot analysis." (PMID 34503223, 2021). "PLK1 interaction with DNA damage response during mitosis and PLK1 inhibition-dependent cell cycle arrest, apoptosis and tumor regression implicate it as a mediator in the crosstalk between cellular signaling and DNA damage and repair." (PMID 34680264, 2021). "ZNF143 positively regulates tumor growth through transcriptional regulation of DNA replication and cell-cycle-associated genes (such as CDC6, PLK1, and MCMs) in multiple solid tumors, including in LCs." (PMID 34616428, 2021). "This major role in cell proliferation appears relevant to stop tumor progression by specific inhibitors of Plk1." (PMID 34646387, 2021).
tumor (continued). "Our results strongly supported the idea that PLK1 holds promise as a therapeutic target in MB and revealed that PLK1 inhibition can reduce tumor cell proliferation and increase apoptosis in MB." (PMID 33494392, 2021). "As shown in the clinical relevance part of this study, TCGA analysis revealed that EGFR and PLK1 expression was relatively higher in the tumor tissues of LUAD patients compared with normal tissues." (PMID 34503223, 2021). "Treatment of mice with the PLK1 inhibitor reduced both ZFP36/TTP phosphorylation in xenograft tumor tissues, and the tumor size." (PMID 33411958, 2021). "c-Myc has been explored as a main transcriptional factor for stemness and ABCB1 expression, while PLK1 is essential for stabilization of c-Myc for tumor survival by phosphorylation-mediated stabilization." (PMID 34503223, 2021). "ATM has been reported to influence the cell cycle through regulation of PLK1, and PLK1 is the G2/M checkpoint that alleviates cell cycle arrest in the G2/M phase in various tumour cells." (PMID 34565365, 2021). "Gene set enrichment analysis (GSEA) indicated that several cell cycle related pathways were highly enriched in tumor compared to matched normal tissues, including PLK1 signaling, E2F transcription factor network, and Aurora A/B signaling." (PMID 34881526, 2021). "A heatmap analysis revealed that EGFR and PLK1 expression was relatively higher in tumor tissues than those in normal tissues." (PMID 34503223, 2021). "In these patients, PLK1 expression was concurrently higher in the tumor tissues than those in normal tissues." (PMID 34503223, 2021). "We have previously shown that silencing the expression of Plk1 efficiently reduced tumor growth rate and prolonged survival of mice bearing ovarian cancer." (PMID 34959480, 2021). "Of these, polo-like kinase 1 (Plk1) showed 2.2-fold downregulated expression in ChREBP−/− mice tumor." (PMID 34685767, 2021). "For example, chitosan-derived carbon, a highly efficient fluorescent nanoparticle, linked to a functionalized siRNA, targets the overexpression of the polo-like kinase 1 (PlK1) gene in tumor cells, which is the basic regulatory factor of mitosis." (PMID 33796026, 2021). "Tumor-suppressor factors such as miRNA-23a diminish PLK1 expression in inhibiting PC proliferation and invasion." (PMID 34943856, 2021). "With the development of PLK1 inhibitors, several PLK1 inhibitors displayed encouraging effect on diverse tumor types by suppressing tumor cell growth." (PMID 32231733, 2020). "Previously, it had been shown that inhibition of both KSP and PLK1 rapidly resulted in mitotic arrest and apoptosis induction, making these two kinases ideal targets for RNAi silencing in tumor cells." (PMID 32785133, 2020). "We therefore analysed the expression of the ER-regulated genes (ERGs) TFF1, GREB1 and PR, together with PLK1, Ki67, PCNA and CENPE (a centromere associated protein that accumulates in G2 phase and is involved in chromosome alignement), in treated tumours." (PMID 32792481, 2020). "Accordingly, the proliferation status of the PDX, measured by PLK1 and Ki67 expression analysis in baseline tumours, was higher in responder PDXs as compared to resistant." (PMID 32792481, 2020). "PLK1 is overexpressed in many human tumour cells and has become a popular drug target in tumour therapy." (PMID 32463161, 2020). "The markers Ki-67 and Plk1 both play an important role in tumor development, progression and in overall prognosis." (PMID 33117692, 2020). "Another group identified PLK1 as a critical signaling pathway required for NB tumor initiating cells' survival." (PMID 32231733, 2020).
tumor (continued). "We are aware that additional independent cohorts of early-stage OC patients, including endometroid, mucinous, and mixed tumor subtypes, need to be analyzed before a clinical use of cDNA arrays for the determination of Ki-67 and Plk1 levels can be recommended." (PMID 33117692, 2020). "As a transcription factor, FOXM1 crosstalk with multiple proteins including PLK1, Cyclin B1 and Aurora B, and thus plays a central role in tumor aggressiveness." (PMID 32047721, 2020). "This assay identified that Polo-Like Kinase 1 (Plk1), a serine/threonine-protein kinase had differential expression of >50% in the sensitive samples compared to resistant tumours." (PMID 32423157, 2020). "In summary, targeting PLK1 lead to a striking tumour regression in three out of fpur CCND1-driven PDX models, while AKT1 and mTOR mutated PDX preferably responded to AKT1 and mTOR inhibitors." (PMID 32792481, 2020). "In many cases, overexpression of PLK1 correlates with poor prognosis, tumorigenicity and aggressiveness, and tumor-initiating cell (TIC) propagation." (PMID 33066048, 2020). "Our previous investigations demonstrated that Ki-67 and Plk1 are expressed in a vast majority of tumor tissues examined." (PMID 33117692, 2020). "We show that PLK1 inhibition results in dramatic tumour shrinkage in highly proliferating CCND1-driven PDX including different RB-positive PDX with acquired palbociclib resistance." (PMID 32792481, 2020). "The levels of USP7 and mitotic markers, including AURKB, CCNB1, and PLK1, were higher in tumor samples than in normal tissues." (PMID 33207738, 2020). "It has been confirmed that PLK1 is overexpressed in many different tumour types and thus has a critical effect on tumour development." (PMID 32463161, 2020). "Subsequent genome editing of PLK1 led to tumor growth suppression, reducing tumor volume by 23.5% compared with the saline-treated control group." (PMID 33353099, 2020). "Then, peptides PLK1121, PLK1122, PLK1345, and PLK1345/9M were evaluated for their capacity to induce CD8 T-cell responses capable of recognising PLK1-expressing tumour cells." (PMID 32595211, 2020). "These nanocomplexes also downregulated expression of PLK1 and induced an indel frequency of 35% at the PLK1 genomic locus in the tumor tissue." (PMID 33353099, 2020). "The use of inhibitors of mitotic regulators, such as taxol or inhibitors of PLK1 (polo like kinase 1) and the Aurora-A/B mitotic kinases, has been demonstrated to promote mitotic stress overload on tumor cells." (PMID 31947935, 2020). "Upon administration into a tumor-bearing mouse model, lipid nanoshells containing genome-editing components suppressed expression of PLK1 protein and exerted anticancer effects." (PMID 33353099, 2020). "Mice were first challenged subcutaneously with C1498-luc, and 7-days later, when tumours reached a size of 3–5 mm diameter the mice received PLK1-derived peptide-loaded DC prime_TriVax booster immunisation with a 7-day interval." (PMID 32595211, 2020). "PLK1 inhibition results in tumour shrinkage in highly proliferating CCND1-driven PDX, including different RB-positive PDX with acquired palbociclib resistance." (PMID 32792481, 2020). "Summarized, whereas PLK2 and PLK3 are considered to be tumor suppressors, PLK1 and PLK4 are associated with carcinogenesis and are often overexpressed in tumor cells." (PMID 33053667, 2020). "The strategy consisted in addressing the tumor trough PSMA, a protein overexpressed in the surface of prostate cancer cells and tumor vascular endothelium, with a PSMA aptamer linked to PLK-1 and BCL-2 siRNAs." (PMID 31888119, 2019). "The knockdown of the oncogenes/proto-oncogenes PLK-1 and survivin also exerted profound tumor cell-inhibitory effects in anchorage-dependent proliferation assays." (PMID 31726756, 2019).
tumor (continued). "Even though the molecular mechanisms of Plk1 in tumor appearance and tumor progression are still under debate, recent studies have shed light on this issue, defining detailed molecular mechanisms on how Plk1 directly participates in the oncogenic signaling." (PMID 30862113, 2019). "Splenocytes derived from these mice were tested for ploidy analysis, showing increased levels of aneuploidy, suggesting a potential mechanism by which reduced levels of PLK1 can be tumor prone." (PMID 30862113, 2019). "Unexpectedly, recent research done with genetically modified mouse models strongly suggests a possible tumor suppressor role for PLK1, placing the oncogenic function of PLK1 under debate." (PMID 30862113, 2019). "Our modeling results on partial Plk1 inhibition offer a cautionary note on targeting Plk1 as a tumor-suppressive strategy." (PMID 30875364, 2019). "Volasertib, presently the most extensively studied Plk1 inhibitor, has been validated to efficiently reduce tumor growth in preclinical settings." (PMID 30859681, 2019). "PLK1 is known as an early activator of the G2/M transition in the cell cycle and is described as a proto-oncogene and overexpressed in many different tumor types." (PMID 31541075, 2019). "The first in vivo evidence showing that Plk1 can play as a tumor suppressor arose in 2008 with the first Plk1 genetic modified mice strain generated by gene-trapping strategies." (PMID 30862113, 2019). "Second, Plk1 can play as a tumor suppressor when combined with certain oncogenes (such as K-Ras, Her2 or APCmin), either by over-expression or by down-regulation strategies." (PMID 30862113, 2019). "PLK1 expression was elevated in tumor tissues with moderate and poor differentiation compared to that in tumor tissues with good differentiation." (PMID 31387297, 2019). "In summary, these data show that Plk1 can indeed play a double game, either cooperating with the tumor progression or being a tumor stopper depending on the tumoral genetic background." (PMID 30862113, 2019). "In preclinical models the anti-tumor activity of PLK1 inhibition through RNA interference have been demonstrated, thus several clinical trials based on the pharmaceutical TKM-080301 were carried out by Tekmira Pharmaceuticals." (PMID 31344836, 2019). "In these studies, high Plk1 expression levels correlated with poor patient prognosis, corroborating its importance in tumor progression and its potential as a therapeutic target." (PMID 31795121, 2019). "PLK1 is a potential target in tumor therapy, because PLK1 is overexpressed in various types of human tumors, and its inhibition is potently antiproliferative for tumor cells." (PMID 30991703, 2019). "TKM-080301 is a lipid nanoparticle formulation of an siRNA against Polo-like kinase 1 (PLK1), which regulates critical aspects of tumor progression." (PMID 31470511, 2019). "The combination of cMet and Plk1 inhibition led to regression of tumors in three models and marked tumor size reduction in the fourth model." (PMID 31040125, 2019). "PLK1 is highly expressed in most malignant tumor cells and is closely related to the occurrence and development of tumors." (PMID 30995921, 2019). "The combination of Plk1 and cMet inhibitors led to tumor regression in both of the PDX models that was statistically significant starting on day 7 (P < 0.05)." (PMID 31040125, 2019). "Plk1 inhibition by volasertib, presently the most extensively studied Plk1 inhibitor, reduced tumor growth with a high efficacy in both in vitro and in vivo settings." (PMID 30859681, 2019). "This review summarizes the proposed mechanisms by which Plk1 can play as an oncogene or as a tumor suppressor, and extrapolates this information to clinical features." (PMID 30862113, 2019).
tumor (continued). "Volasertib, at present the lead agent in the category of Plk1 inhibitors, has been shown to induce mitotic arrest and cell death with a high efficacy in vitro, and to inhibit tumor growth in xenograft models." (PMID 31795121, 2019). "While inhibitors of PLK1 such as volasertib have been shown to reduce the proliferation of rapidly dividing tumor cells both in vitro and in vivo, its possible role in PAH has received little attention." (PMID 31437238, 2019). "Surprisingly, when Plk1 activity is inhibited, the ER-dependent gene sets that were downregulated correlate with tumor-suppressive functions." (PMID 30862113, 2019). "Nevertheless, using a fractionated irradiation schedule with repeated Plk1 inhibition, a significant improvement in local tumor control was observed when compared to irradiation alone." (PMID 31795121, 2019). "Strikingly, when Plk1 inducible expression in mammary glands was combined with mice strains carrying either the K-Ras or Her2 oncogenes, tumor incidence was dramatically reduced in both cases, up to 85% and 50%, respectively." (PMID 30862113, 2019). "We found that 60% (18/30) of samples with high PLK1 expression (above median PLK1 TPM of all tumor samples) also had high β-catenin (CTNNB1) expression (above median CTNNB1 TPM of all tumor samples)." (PMID 31741706, 2019). "The inhibition of PLK1 expression by PLK1 siRNA can lead to death of tumor cells with multiple stages of mitosis, and therefore PLK1 is expected to be one of potential targets for siRNA therapy against tumors." (PMID 30991703, 2019). "Clinical data show that inhibition of PLK1 can prevent the proliferation and promote the apoptosis of tumor cells." (PMID 30995921, 2019). "Although there is a collection of scientific reports showing how Plk1 can contribute to tumor progression, recent data from different laboratories using mouse models, show that Plk1 can surprisingly play as a tumor suppressor." (PMID 30862113, 2019). "AURKA and PLK1 expression levels are elevated in tumor tissues compared to adjacent normal tissues in patients with HCC." (PMID 31214512, 2019). "We first evaluated the gene silencing efficiency of human PLK1-targeted siRNA (sihPLK1)-loaded uPIC (sihPLK1/uPIC) in the tumour tissue." (PMID 31019193, 2019). "All these features led the scientific community to consider Plk1 as an oncogene over decades, despite its contribution to tumor development still being uncertain." (PMID 30862113, 2019). "Correlation analysis of Plk1 expression with patient overall survival demonstrates that Plk1 overexpression leads to different outcomes depending on the tumor type." (PMID 30862113, 2019). "High PLK1 expression was correlated with a worse prognosis in tumor tissues with both good (AHR = 4.32, p = 0.026) and moderate/poor (AHR = 1.57, p = 0.026) differentiation." (PMID 31387297, 2019). "We observed that PLK1 expression was higher in tumor tissues than that in adjacent normal tissues of OSCC patients." (PMID 31387297, 2019). "Intratumoral injections of LP-HAPC-2mol%FA-PEG2000 lipoplexes with PLK1 siRNA inhibited tumor growth compared with the Cont siRNA, although the difference was not significant." (PMID 30991703, 2019). "The proposed mechanism by which Plk1 halts tumor appearance relays on the induction of severe polyploidy upon Plk1 overexpression." (PMID 30862113, 2019). "Strikingly, Plk1 overexpression prevented tumor development by KrasG12D in 85% of the mouse colony and significantly delayed tumor latency in the rest of the colony." (PMID 30069007, 2018). "First, PLK1 inhibition is capable of boosting tumor antigen presentation and antitumor immune infiltration, which can be further augmented by the addition of immunotherapy." (PMID 30631355, 2018).